INS (insulin)
Diseases named in the same sentence as INS in open-access papers (continued):
Sharing a sentence is not in itself a finding about the gene and the disease.
diabetes (continued). "The Diabetes UK-funded Counterpoint study suggested that this should be sufficient to reverse T2DM by removing ectopic fat in liver and pancreas, restoring first-phase insulin secretion." (PMID 26879684, 2016). "Diabetes mellitus is a metabolic disorder that is characterized by high blood glucose level, and body cannot produce enough insulin, or does not respond to the produced insulin." (PMID 28197516, 2016). "MSC transplantation increased plasma and islet insulin contents in non-obese diabetic (NOD) mice with severe diabetes." (PMID 27905403, 2016). "For example, results from the FREEDOM Trial showed that in patients with diabetes and multi-vessel coronary artery disease, MACEs were higher in patients treated with insulin compared to patients without insulin therapy." (PMID 27887590, 2016). "During the development of type 2 diabetes mellitus (T2DM), insulin signaling in the target tissues is impaired, and in order to overcome this resistance, the β cells of the pancreas begin to proliferate and produce more insulin." (PMID 27478532, 2016). "Pre-activated T cells and incipient insulin-reactive T cells in response to porcine or human insulin were identified in non-diabetic dogs and in dogs with diabetes." (PMID 27031512, 2016). "Diabetes mellitus is a disease lack of insulin, which has severely delayed and impaired wound healing capacity." (PMID 27042331, 2016). "Once the damage to β-cells exceeded from threshold, the pancreas is not able to secrete a sufficient amount of insulin and consequently due to high blood glucose diabetes mellitus would be inevitable." (PMID 27980584, 2016). "Knowing that conditions occurring with hyperinsulinemia in vivo (metabolic syndrome, obesity or diabetes) impair fertility, the use of insulin in non-physiological doses should be used cautiously." (PMID 27766972, 2016). "Type 2 diabetes (T2D) is another form of diabetes mellitus, where body either does not produce enough insulin or body is resistant to insulin action." (PMID 27767104, 2016). "One-half of all patients were taking insulin with or without an oral glucose-lowering agent for diabetes and one-half were taking a fibrate with or without fish oil or a statin for hypertriglyceridemia." (PMID 27642538, 2016). "The UK Practical Classification Guidelines for Diabetes published by the Royal College of General Practitioners and (the previously existing) NHS Diabetes are pragmatically based on age at diagnosis and time from diagnosis to commencing insulin treatment." (PMID 27080317, 2016). "Furthermore, with longer durations of diabetes and progressive β-cell deterioration, most patients with T2DM will eventually require insulin to control glucose levels effectively, and prevent diabetes-related complications." (PMID 27417914, 2016). "In a healthy situation, insulin prevents lipolysis and inhibits hepatic gluconeogenesis, but not in diabetes or in the metabolic syndrome." (PMID 27486806, 2016). "Overnight, 24-h fasting, and after a mixed meal, urine collection studies demonstrated the value of urinary C-peptide as non-invasive measure for endogenous insulin secretion in people with and without diabetes." (PMID 26526605, 2016). "In line with this, the analysis of the clinical and biochemical parameters at baseline and at 12 months after LRYGB of 30 out of our 75 patients without second liver biopsy also showed a significant improvement of fasting insulin, glycaemia, HOMA-IR, metabolic syndrome, diabetes, and CRP." (PMID 27594839, 2016). "In most publications, insulin was the drug of choice for pregnant women whose diabetes was not controlled by diet alone." (PMID 27803934, 2016). "These cells continue to secrete too much insulin, but it does not seem to be enough, and the patient develops diabetes." (PMID 26985241, 2016).
diabetes (continued). "The low levels of C-peptide in our population demonstrates the failure of pancreatic beta cells in patients living with a diabetes diagnosis for over 10 years and confirms the concept that T2DM patients often require the use of exogenous insulin to achieve glycemic control." (PMID 26909482, 2016). "Smokers tend to lose weight in comparison with non-smokers, and lower weight is protective against diabetes and improves insulin sensitivity." (PMID 26954355, 2016). "Randomized controlled trials (RCTs) that investigated the effect of caffeine on insulin sensitivity in healthy humans without diabetes were included." (PMID 28031026, 2016). "We did not exclude women with: diabetes not prescribed insulin, unmedicated epilepsy, glucose-6-phosphate dehydrogenase deficiency, sickle cell anaemia, maternal hypertension." (PMID 27906972, 2016). "The use of STZ has the advantage of a standardized protocol, onset and development of diabetes, but does not fully replicate T1D as it usually does not induce ketosis and does not necessitate insulin therapy." (PMID 27618031, 2016). "Therefore, high adiponectin and/or low leptin levels can enhance insulin sensitivity in WAT and increase FAO in the liver, thus leading to the improvement of diabetes." (PMID 27589792, 2016). "Because CTe treatment resulted in an increase in insulin in the DIO mouse model, we believe that CTe treatment could prevent diabetes." (PMID 26989693, 2016). "In the present analysis of male employees without treated diabetes and mental disorder, VFA and fasting insulin, but not SFA, were significantly associated with EDS after multivariable adjustment." (PMID 26891344, 2016). "In the clinical setting, given the potential adverse effects of thiazolidinediones and biguanides, we often have difficulty in treatment that no other insulin sensitizers are available for use in type 2 diabetic mellitus (T2DM) patients." (PMID 26640808, 2016). "Recent studies report that mice lacking glucagon receptor (Gcgr-/-) do not develop diabetes following streptozotocin (STZ)-mediated ablation of insulin-producing β-cells." (PMID 27092792, 2016). "Of those excluded, one had insufficient serum for assessing vitamin B12 concentration, twelve had missing information on diabetes-related questions, seven were non-diabetic but taking metformin, and one was non-diabetic but taking insulin." (PMID 27513580, 2016). "First, the database examined did not allow for the linkage of diagnosis and prescription data directly; therefore, it was difficult to ensure patients’ utilization of insulin was truly for diabetes rather than glucose toxicity." (PMID 26759271, 2016). "Worldwide 314 million individuals are suffering from (metabolic disorder) type-2 diabetes mellitus, which has been classified as a disease of glucose overproduction by tissues lacking enough insulin production." (PMID 27304951, 2016). "Currently, major organizations recommend that SFA be replaced with MUFA or PUFA, largely to improve lipid profiles rather than glucose-insulin metrics, for the primary and secondary prevention of diabetes." (PMID 27434027, 2016). "Non-aggressive bihormonal and insulin-alone closed-loop systems were compared in a paediatric diabetes camp over three consecutive nights." (PMID 27364997, 2016). "Type 2 diabetes mellitus (T2DM) is a chronic metabolic disease that is characterized by high blood glucose levels, relative insufficiency of insulin secretion from pancreatic beta cells and insulin resistance." (PMID 26831044, 2016). "Because her diabetes mellitus turned out to be T1D, she received subcutaneous insulin injection therapy and did not resume vildagliptin." (PMID 27520566, 2016). "High circulating nonesterified fatty acids (NEFAs) concentration, often reported in diabetes, leads to impaired glucose-stimulated insulin secretion (GSIS) through not yet well-defined mechanisms." (PMID 27366756, 2016).
diabetes (continued). "Given that systemic control of diabetes facilitates corneal epithelial wound healing, does topical insulin have an effect independent of systemic glucose control?" (PMID 27703986, 2016). "PD-1/PD-L1 deficiency on a diabetes-prone background (NOD) led to accelerated disease as previously reported, and increased numbers of insulin-specific but not foreign antigen-specific CD4+ T cells in the SLO and pancreas." (PMID 27656680, 2016). "Of the 8175 participants in TILDA, 634 participants reported a previous doctor diagnosis of diabetes and 38 participants did not report a diagnosis of diabetes but were classified as having diabetes by the use of oral hypoglycaemic agents or insulin." (PMID 27294152, 2016). "Among the patients with previously diagnosed diabetes, 11 (7.86%) had no treatment, 119 (85%) take oral anti-diabetic agents, 14 (10%) were treated with insulin, 38 (27.14%) were treated with diet therapy, and four (2.86%) used traditional medicine." (PMID 27213415, 2016). "Diabetes is a group of metabolic diseases that occur either when the pancreas does not produce enough insulin or when the body cannot effectively use the insulin it produces due to decreased insulin sensitivity." (PMID 27257845, 2016). "There is no screening for neonatal diabetes, but the clinical suspicion avoids the metabolic decompensation and allows early initiation of insulin therapy." (PMID 27909691, 2016). "Variables associated with being discharged on insulin therapy (versus no insulin therapy) in liver transplant patients without a pretransplant history of diabetes mellitus." (PMID 28031946, 2016). "The percentage of BGTS users not on a diabetes therapy (27.4 %) far outnumbered those on an insulin-only regimen (7.3 %) and remained greater even when those using non-insulin diabetes therapy in combination with insulin were factored in (18.4 %)." (PMID 26972690, 2016). "Addition of HN improved insulin sensitivity in animal models of diabetes mellitus but no clinical studies have been carried out to measure HN levels in humans associated with hyperglycemia." (PMID 27173674, 2016). "The goodness-of fit-test, as determined by 200 bootstraps of Pearson’s chi-square, indicated lack of fit in the general diabetes subscale (P = 0.02) and no lack of fit in the insulin-use subscale (P = 0.06)." (PMID 27366112, 2016). "Similarly, significant associations were found between the number of ELC and BMI, hypertension, HDL cholesterol, insulin levels, HOMA-IR and diabetes." (PMID 26790748, 2016). "Diabetic mice were maintained without insulin supplementation to allow for the progression of severe diabetes and the appearance of its complications, including DR." (PMID 26983784, 2016). "Nowadays, such methods as taking antidiabetic medicines or injecting insulin to cope with diabetes are the usual practice, but there is no way of thorough treatment." (PMID 27242389, 2016). "A randomized double blind placebo controlled trial was carried out to investigate the efficacy of T. crispa as an additional treatment in patients with type 2 diabetes mellitus who refused insulin injection and did not respond to oral hypoglycemic drugs." (PMID 27047378, 2016). "Apparently, the dynamics of Inpp5f during the diabetes development in the STZ model did not correlate with the insulin, glucose and lipid levels." (PMID 26908121, 2016). "Another explanation for the increased sensitivity of SOCS-3 transgenic mice to MLDSTZ-induced diabetes is that SOCS-3 overexpression could obstruct normal β-cell functioning, for instance, by interfering with JAK/STAT-dependent insulin signaling." (PMID 27242781, 2016). "Type 1 diabetes mellitus is an autoimmune-mediated disease, characterized by destruction of most, if not all, of the insulin-producing capacity of pancreatic beta-cells." (PMID 26521082, 2016).
diabetes (continued). "Insulin and IGF signaling are critical to numerous developmental and physiological processes, with perturbations being pathognomonic of various diseases, including diabetes." (PMID 27919317, 2016). "As an example in the UK, compared with insulin starters, those initiating a GLP-1RA therapy had higher body mass index (BMI) and better glycaemic control at baseline, and were younger with shorter duration of diabetes." (PMID 27019360, 2016). "The objective of this paper is to investigate the effects of liraglutide in combination with short-term continuous subcutaneous insulin infusion (CSII) therapy on glycemic control and beta cell function in patients with newly diagnosed type 2 diabetes mellitus (T2DM)." (PMID 26640805, 2016). "One important difference between the non-diabetic group (IS + IR) and type 2 diabetes mellitus group is their insulin sensitising and anti-inflammatory medication (metformin)." (PMID 27342408, 2016). "Since no complete vanin inhibition could be achieved in mice, we used the ZDF-diabetes rats as an animal model for diabetes to evaluate the effects of RR6 on hepatic steatosis and insulin sensitivity." (PMID 26932716, 2016). "Diabetes mellitus is a chronic disease where the pancreas does not produce enough insulin or when the body cannot use the insulin it produces effectively." (PMID 26999166, 2016). "Efficacy evaluation of treatment with diabetes commonly uses hemoglobin A1c (HbA1c); however, the level of this index does not allow for evaluation of treatment effects on insulin secretion or insulin resistance." (PMID 26925169, 2016). "The aim of present study was to investigate whether glucose metabolism and insulin sensitivity were impaired in the MDD patients, and to identify the potential mechanisms linking MDD with prediabetes and subsequent diabetes." (PMID 27274905, 2016). "The EGIR-diagnosis selects an upper quartile of fasting insulin and excludes prevalent diabetes, resulting in a lower prevalence compared to the other definitions." (PMID 27117940, 2016). "It is consequently not surprising that most research has been focused on insulin and its actions in the search for improved strategies for optimizing blood glucose control and preventing secondary diabetes complications." (PMID 27044660, 2016). "This small trial showed that a Palaeolithic diet decreased fasting plasma leptin, but did not affect fasting levels of insulin, C-peptide, glucagon, incretins, ghrelin and adipokines significantly compared to the currently recommended diabetes diet." (PMID 27216013, 2016). "While most overweight or obese youth are insulin resistant, diabetes does not develop unless beta cell dysfunction supervenes." (PMID 28702252, 2016). "In conclusion, the exploratory analyses indicate that, when controlling for diabetes medication, supplementation with CDNC appears to improve insulin sensitivity by reducing blood levels of insulin and glucose as well as the oxidative stress and inflammation associated with diabetes." (PMID 27687012, 2016). "Levels of C-peptide were higher in patients with postpartum development of IGT or type 2 diabetes mellitus than in patients without postpartum glucose intolerance, indicative of increased insulin resistance and increased insulin secretion in the former group." (PMID 27223471, 2016). "The 52-week monotherapy with the dipeptidyl peptidase-4 inhibitor sitagliptin and the sulphonylurea glimepiride on early-phase insulin secretion in Japanese patients with type 2 diabetes mellitus (T2DM) is not known." (PMID 26925169, 2016). "Diabetes mellitus is a group of diseases characterized by hyperglycemia due to lack of insulin or disturbances in insulin signaling." (PMID 27223471, 2016). "Average diabetes years of using combined OAD and insulin group was 8.50 years." (PMID 27904812, 2016). "Small short-term intervention studies reported increases in insulin and plasma glucose or glycated albumin in hyperlipidaemic patients without diabetes." (PMID 26577796, 2016).
diabetes (continued). "Insulin treatment failed to prevent oxidative stress in the testis with outcomes being similar to those in untreated diabetes (Ins compared to STZ and control)." (PMID 27869771, 2016). "A decline in beta cell insulin secretion contributes to the later stages of diabetes, but it is not known what, if any, functional beta cell changes occur in prediabetes and early disease." (PMID 27048248, 2016). "In line with the notion of MAPT expression in non-CNS tissue including the pancreas, an analogy between AD and type 2 diabetes mellitus (T2DM) has been suggested, in particular with respect to insulin signaling pathway dysfunction, protein aggregation, and oxidative events." (PMID 26824039, 2016). "Intensive insulin therapy resulted in lower glycated hemoglobin (A1c), reduced CVD events and mortality in the Diabetes Control and Complications Trial (DCCT)/Epidemiology of Diabetes Interventions and Complications (EDIC) study." (PMID 27099615, 2016). "Diabetes mellitus (DM) is a complex, chronic illness in which there is an absolute or relative lack of insulin." (PMID 27446205, 2016). "Finally, there is evidence for linking “ERK/MAPK Signaling” to diabetes, as it was shown that MAPK/ERK signaling controls glucose metabolism by regulating insulin sensitivity in Drosophila." (PMID 27019061, 2016). "The BG or diabetes diary, which is often paper-based, is an essential component of flexible MDI, as it enables comparison to BG targets and enables BG trends to be analysed to inform proactive changes in insulin formula." (PMID 27629774, 2016). "This suggests that the high blood sugar levels seen in diabetes result from an excess of glucagon, and not a lack of insulin." (PMID 27092792, 2016). "Interestingly, the dynamic change in glucose and insulin during OGTT was higher in those who reported warm hands than in “Cold” respondents, even though participants were diabetes and hypertension-free." (PMID 27818698, 2016). "In diabetes and obesity, insulin no longer suppresses hepatic gluconeogenesis, while continuing to activate lipogenesis, a state referred to as ‘selective insulin resistance'." (PMID 27708333, 2016). "Over a 3-month study period, a Palaeolithic diet resulted in reduced fasting plasma leptin levels, but did not change fasting levels of insulin, C-peptide, glucagon, incretins, ghrelin and adipokines compared to the currently recommended diabetes diet." (PMID 27216013, 2016). "The pathobiology of diabetes is not homogenous and ranges from insufficient insulin synthesis to altered tissue sensitivity." (PMID 26635356, 2016). "Diabetes mellitus is well known as a chronic metabolic disease that is characterized by a relative or absolute lack of insulin, resulting in hyperglycemia." (PMID 27595114, 2016). "In Denmark, the difference between the once-daily insulin regimen health state and ‘well controlled diabetes’ was not significantly different from zero (−0.01, 95 % CI −0.012, −0.003)." (PMID 26801908, 2016). "In addition, multiparity was higher in the insulin-group and a higher proportion had a previous GDM, previous infant weighing ≥4500 g at birth, and a family history of diabetes." (PMID 27680327, 2016). "Prior work has shown increased insulin sensitivity and oxidative capacity in skeletal muscle of trained endurance athletes, as opposed to the skeletal muscle of diabetics, which has lower insulin sensitivity and oxidative capacity." (PMID 27445983, 2016). "Although insulin has remained an important component in treatment plans for DM management in patients with type 1 diabetes mellitus (T1DM), it fails to prevent the long-term complications." (PMID 27164129, 2016). "Despite extensive clinical experience with a variety of insulin types, no prospective studies have addressed the relative efficacy of specific insulin regimens for treating posttransplant diabetes." (PMID 28702248, 2016).